TNF (tumor necrosis factor)
Diseases named in the same sentence as TNF in open-access papers (continued):
Sharing a sentence is not in itself a finding about the gene and the disease.
atherosclerosis (continued). "The downregulation of IL4, CXCL10, MCP1, TNFα, and estradiol and CSF3 upregulation may mediate the adaptation of adiponectin-deficient males to HFD-induced atherosclerosis." (PMID 38201205, 2023). "In the case of atherosclerosis, T lymphocytes and macrophages accumulate and proliferate at the atherosclerotic lesions, which leads to the secretion of inflammatory cytokines such as TNF-α and IL-10." (PMID 36768722, 2023). "In addition, increased BPV can also promote the secretion of tumor necrosis factor-α (TNF-α) from monocytes and macrophages to increase the transport of low-density lipoproteins across endothelial cells and accelerate the process of early atherosclerosis." (PMID 35369353, 2022). "The occurrence of atherosclerosis is closely related to the activation of TNF-α." (PMID 39050559, 2022). "On the other hand, TNF-α can inhibit lipoprotein lipase and reduce the oxidative metabolism of fatty acids, thus leading to hypertriglyceridemia and stimulating the reactive oxygen species production, thus promoting atherosclerosis development." (PMID 36685487, 2022). "Second, hyperhomocysteinemia might contribute to the development of atherosclerosis by increasing tumor necrosis factor expression, increasing oxidative stress and inducing a proinflammatory vascular state." (PMID 36291435, 2022). "Considering the fact that inflammation has a key role in the development of atherosclerosis, we further investigated whether capsaicin administration could ameliorate inflammation in ApoE−/− mice, and the levels of IL-1β, IL-6, TNF-α were detected in serum." (PMID 36297020, 2022). "It has been anteriorly described that the expression of IL-37 is involved in the pathogenesis of atherosclerosis and that this biomarker has an inflammatory effect by reducing the expression of other inflammatory cytokines, such as interleukin-18 (IL-18) and TNF-α." (PMID 36012430, 2022). "In addition, KEGG pathway analysis revealed that DEGs are mainly involved in the complement and coagulation cascades, fluid shear stress and atherosclerosis, and TNF signaling pathway." (PMID 36345357, 2022). "Furthermore, the KEGG results showed that the differentially expressed FRGs were mainly enriched in ferroptosis, IL-17 signaling pathway, TNF-signaling pathway, and lipid and atherosclerosis." (PMID 36110200, 2022). "Clinical and pre-clinical evidence support the pivotal role of chronic inflammation and endothelial dysfunction in accelerating the process of atherosclerosis, driven by proinflammatory cytokines such as interleukin 6 (IL-6) and tumor necrosis factor alpha (TNF-alpha)." (PMID 36352850, 2022). "Those genes were significantly related with KEGG pathway of “AGE-RAGE signaling pathway in diabetic complications” (p = 2.88E-22), “fluid shear stress and atherosclerosis” (p = 2.94E-20), “IL-17 signaling pathway” (p = 5.69E-20), and “TNF signaling pathway” (p = 1.02E-19) in the healing process." (PMID 35935848, 2022). "The role of TNF-α in atherosclerosis has been extensively investigated." (PMID 35571620, 2022). "At the same time, the KEGG enrichment analysis also suggested at the TNF signaling pathway, lipid and atherosclerosis, MAPK signaling pathway, IL-17 signaling pathway, PI3K-Akt signaling pathway, and other pathways played an important role in the occurrence and development of IS." (PMID 35685645, 2022). "IL6, CXCL8, CCL2, SOD2, NFKBIA, and BIRC3 were identified as the top 6 hub genes in the magenta module (human cardiomyocyte samples) and were mainly enriched in the NOD-like receptor signaling pathway, IL-17 signaling pathway, TNF signaling pathway, lipid and atherosclerosis signaling pathway." (PMID 36426222, 2022). "Furthermore, PA can restrain secretion and production of TNF-α, which is involved in the pathogenesis of atherosclerosis and heart failure." (PMID 35958867, 2022). "The role of TNF-α in atherosclerosis has been documented experimentally." (PMID 36555579, 2022).
atherosclerosis (continued). "Therefore, TNFα is a key atherosclerotic cytokine in atherosclerosis and its genetic deletion in atherogenic Apoe−/− mice fed 10 weeks of WD was found to decrease atherosclerotic lesion size by 50% compared to control Apoe−/− animals." (PMID 35600479, 2022). "In addition, KEGG analysis showed that the DEGs were mainly enriched in Staphylococcus aureus infection, TNF signaling pathway, Tuberculosis, Osteoclast differentiation, and Fluid shear stress and atherosclerosis." (PMID 35693550, 2022). "In addition, Lipid and atherosclerosis, Fluid shear stress and atherosclerosis, IL-17 signaling pathway and TNF signaling Pathway play an important role in this pathophysiological process." (PMID 36441671, 2022). "We found that Tat treatment can affect several other pathways including cytokine-cytokine receptor interaction, TNF signaling pathway, HIF-1 signaling pathway and Jak-STAT signaling pathway that may also be associated with HIV Tat-induced atherosclerosis." (PMID 33459922, 2022). "However, high levels of TNFα and IL-1β in patients with atherosclerosis have been shown to decrease the expression of KLB." (PMID 36006939, 2022). "Clinical studies included a more extensive list of diverse biomarkers associated with atherosclerosis development to include TNF-α, VCAM-1, ICAM-1, and several interleukins, which were not as extensively studied in observational studies." (PMID 36232062, 2022). "Oxidative stress is a key mechanism linked to endothelial dysfunction, decreased NO and promotion of inflammatory cytokines such as tumor necrosis factor-α and interleukin factors, all of which can lead to pathophysiological processes of atherosclerosis in heart disease and neurological conditions." (PMID 35566133, 2022). "The inflammatory suppression role of SLPI may confer protection against atherosclerosis by neutralizing the effect of inflammatory factors such as TNF-α or by blocking the activation of NF-κB." (PMID 36299596, 2022). "During atherosclerosis, TNF promotes an inflammatory cascade that occurs within the artery wall." (PMID 36703734, 2022). "Considering the role of TNF-α in inflammation and atherosclerosis, the use of TNFis may lead to a reduction in cardiovascular risk in patients with axSpA." (PMID 35698171, 2022). "Thus, the dual role of TNF-α/IFN-γ, especially TNF-α, also contributes significantly to psoriatic lesion inflammation and atherosclerosis formation." (PMID 35514987, 2022). "TNF-α is present at every stage of the progression of atherosclerosis." (PMID 35630041, 2022). "However, the effect of TNF-α inhibitors, such as etanercept, adalimumab, and infliximab, in atherosclerosis has been evaluated mostly preclinically or in studies of patients with rheumatological diseases." (PMID 36555579, 2022). "TNFα is a strong inflammatory cytokine that is also upregulated in atherosclerosis." (PMID 36294369, 2022). "In addition, H. pylori releases many cytokines, including interleukin-6 (IL-6), tumor necrosis factor-α (TNF-α), IL-1 and free radicals, causing atherosclerosis and oxidative stress." (PMID 35992650, 2022). "Nevertheless, until recently the therapeutic potential of TNFα blockage in atherosclerosis by pharmacological inhibitors such as monoclonal antibodies remained unknown." (PMID 35600479, 2022). "TNF-α inhibition could represent an appealing anti-inflammatory approach in the setting of atherosclerosis." (PMID 36555579, 2022). "Increases in the amount of PA observed in the AE group and higher CRF in the COMB group were related to reduced levels of ICAM-1, which is a pro-inflammatory molecule promoted by IGF and TNF-α and highly expressed in endothelial cells and related to atherosclerosis." (PMID 35529777, 2022).
atherosclerosis (continued). "The DENRGs were particularly involved in necroptosis, lipids and atherosclerosis, TNF signaling pathway, legionellosis, cytosolic DNA-sensing pathway, RIPK1-mediated regulated necrosis, TRAIL signaling, Kaposi sarcoma-associated herpesvirus infection, and the NLRP3 inflammasome." (PMID 35991562, 2022). "In addition to macrophages, senescent T cells with CD8+CD57+CD27-CD28null phenotype, through producing large amounts of IFN-γ and TNF-α, promote inflammation and development of atherosclerosis." (PMID 36059478, 2022). "Therapeutic strategies directly targeting proinflammatory cytokines [e.g. tumor necrosis factor-alpha (TNF-α), interleukin-1-beta (IL-1β) neutralization, methotrexate and colchicine] have shown great promise in experimental and clinical studies in atherosclerosis." (PMID 35758143, 2022). "Furthermore, studies have revealed that chronic As exposure would lead to positive regulation of tumor necrosis factor- alpha (TNF-α) mRNA and other related factors, and then to atherosclerosis and skin lesions." (PMID 35410083, 2022). "“TNF-α-activated signal transduction pathways” in the cardiovascular system may contribute to vascular dysfunction, development, and progression of atherosclerosis and adverse cardiac remodeling following myocardial infarction and heart failure." (PMID 36035865, 2022). "Combined with the relevant literature, GO and KEGG enrichment analyses are directed to find that the PI3K-AKT signaling pathway, TNF signaling pathway, and fluid shear stress and atherosclerosis signaling pathway are the key pathways of IQPBC in the treatment of AMI." (PMID 35656461, 2022). "Moreover, the pathways enriched in GSEA mainly involved complement and lectin cascades, NETs, lipid and atherosclerosis, TNF signaling pathway, Toll-like receptor signaling pathway, and NOD-like receptor signaling pathway." (PMID 35722467, 2022). "TNF-α activates endothelial cells and induces monocytes/macrophages to express cytokines and chemokines, which may lead to the progression of atherosclerosis." (PMID 36060429, 2022). "To determine whether macrophage inflammation is involved in Hcy-related atherosclerosis, we detected F4/80 (a positive marker of macrophages) and proinflammatory cytokines (IL-1β, IL-6, and TNF-α) in the aortic root of ApoE−/− mice." (PMID 34725437, 2022). "KEGG enrichment analysis screened out 178 signaling pathways, which were mainly enriched in the lipid and atherosclerosis, AGE-RAGE signaling pathway in diabetic complications, fluid shear stress and atherosclerosis, hepatitis B, prostate cancer, TNF signaling pathway, and IL-17 signaling pathway." (PMID 35097123, 2022). "It has been reported that TNF-a is implicated in the decrease in HDL levels, indicating a link between inflammation and the development and progression of insulin-resistant conditions, including NASH and atherosclerosis." (PMID 35739957, 2022). "Additionally, we observed an increase in the secretion of progressive atherosclerosis cytokines, such as IL-6, IL-1β, and TNF-α, in the ox-LDL treated HUVEC supernatants." (PMID 35137664, 2022). "Literature reports have demonstrated that atherosclerosis is a chronic inflammatory disease, with the characteristic of inflammatory cell infiltration and secretion of various inflammatory factors, including TNF-α, IL-6, and IL-1β." (PMID 36176426, 2022). "Moreover, treatment of atherosclerosis-prone mice with the HDAC inhibitor increased the TNF expression and aggravated the neointimal lesions in arteries." (PMID 35371012, 2022). "EBV may also be involved in the atherosclerosis by triggering IL-6 and TNF-α secretion by macrophages, intercellular adhesion molecule-1 (ICAM-1) expression on ECs and lipid profile alternations in blood." (PMID 36059478, 2022). "However, in atherosclerosis, as well as in TNFα-induced brain injury in murine models, the importance of Vcam-1 activation was much more substantial than that of Icam-1." (PMID 35177109, 2022).
atherosclerosis (continued). "In addition, both KEGG and GSEA were enriched in fluid shear stress and atherosclerosis, and tumor necrosis factor (TNF) signaling pathway." (PMID 34956318, 2021). "TNF-α is a multifunctional inflammatory cytokine that may play a part in the pathogenesis of atherosclerosis." (PMID 33627760, 2021). "TNF-α is certainly a crucial molecule in the process of atherosclerosis." (PMID 34829740, 2021). "Some risk factors such as dyslipidemia, oxidized lipids, and cytokines can activate polarization of M1 macrophages that secrete proinflammatory cytokines such as TNF-α, IL-6, IL-1β, and iNOS, thereby creating inflammatory environment and promoting the development of atherosclerosis." (PMID 34901005, 2021). "Thus, the relationship between HSPs and inflammatory cytokines in atherosclerosis progression needs to be further explored using IL-6 and TNF-alpha knockout mice in the future." (PMID 33782520, 2021). "Their finding suggested IFN-γ/TNF-α synergy may provide a critical pro-inflammatory link between psoriatic skin inflammation and distant vessel atherosclerosis." (PMID 34122426, 2021). "Experimentally induced atherosclerosis caused a significant increase in the gene expression of COX-2, iNOS, and TNF-α compared to the control group, while stem cells treatment significantly reduced their levels compared to the atherosclerotic and resveratrol groups." (PMID 34037094, 2021). "Since inflammation-driven endothelial dysfunction is a prime trigger in atherosclerosis initiation and exacerbation, compounds that attenuate TNF-α- induced NF-κB activation and subsequent expression of inflammatory markers are potential therapies to vascular endothelial dysfunction." (PMID 34830366, 2021). "In addition to LPS, microbiota can also regulate the levels of inflammatory cytokines, such as interleukin-6 (IL-6), Interleukin-8 (IL-8), and tumor necrosis factor α (TNF-α), thereby indirectly affecting atherosclerosis progression." (PMID 33897472, 2021). "There is abundant evidence from animal studies showing that SGLT2 inhibitors slow down the progression of atherosclerosis and exert an anti-inflammatory effect by reducing the expression of proinflammatory cytokines, including TNF-α, IL-1β, IL-6, MCP-1, ICAM, VCAM." (PMID 34885795, 2021). "Anti-TNF treatment may, at least transiently, improve endothelial function, atherosclerosis, and arterial stiffness." (PMID 34680168, 2021). "TNF-α can prompt such a phenotypic switching, again contributing to atherosclerosis progression." (PMID 33770265, 2021). "TNF-alpha and IFN-γ have also been associated with the disruption of endothelial cell junctions, leading to leukocyte transmigration, vascular permeability, and matrix degradation, all of which facilitate atherosclerosis development." (PMID 34205487, 2021). "Interestingly, TNF-alpha and CX3CR1 expression positively correlated with increased intima-media thickness and hs-CRP, both of which are markers of atherosclerosis and cardiovascular risk." (PMID 34439835, 2021). "Ezetimibe debilitates atherosclerosis caused by lipid-lowering and reduces circulating inflammatory cytokines in the lesion focuses such as monocyte chemoattractant protein (MCP-1) and tumor necrosis factor (TNF-α)." (PMID 34209109, 2021). "In our study, DLT significantly reduced inflammatory factor IL-6 and TNF-α levels in AS model, activated autophagy of vascular adventitial fibroblasts, which may be part of its anti-atherosclerosis mechanism." (PMID 34867337, 2021). "In the HIVneg group, IL-27, IL-17C and CCL26 remained significantly associated with subclinical atherosclerosis following the regression analysis (p=0.041, p=0.012 and p=0.016, respectively), whereas IL-32θ and TNF-α were no longer significant." (PMID 33936102, 2021). "Furthermore, TNF-α, a proinflammatory cytokine, is known to regulate leukocyte adhesion and migration in vascular inflammatory diseases including atherosclerosis." (PMID 34257685, 2021).
atherosclerosis (continued). "Numerous studies have shown that the proliferation and migration of VSMCs play an adverse role in early atherosclerosis and intimal hyperplasia, which could be triggered by inflammatory cytokines, including TNFα." (PMID 34853629, 2021). "Besides their role as antigen-presenting and Ig-secreting cells, B cells secrete cytokines, which have the potential to either promote (TNFα, INFγ, IL-12) or ameliorate (IL-2, IL-4, IL-10, TGFβ) the development of atherosclerosis." (PMID 33572939, 2021). "The MIS was positively correlated with age, the number of hospitalizations, the presence of atherosclerosis, ferritin, IL-6, TNF-α, CRP and MIAS and inversely correlated with the BMI, albumin, prealbumin, hemoglobin, transferrin, creatinine and blood phosphorus." (PMID 33413177, 2021). "It is known that ox-LDL, TNF-α, IL-6, and other atherosclerosis stimuli remain at a high level in ACS patients for a long time, which may lead to the adaptive upregulation of the expression and activity of antioxidant enzymes in the affected cells." (PMID 34327240, 2021). "B. vulgatus attenuated atherosclerosis through Foxp3 upregulation and TNFα downregulation." (PMID 34531862, 2021). "Atherosclerosis is an inflammatory process of the artery walls and TNF-α as a proinflammatory cytokine triggers nuclear factor kappa-B inflammatory pathway and is involved in an accelerated development of vascular endothelial inflammation and atherosclerosis." (PMID 34976297, 2021). "In addition to vascular calcification, TNF-α contributes to the progression of atherosclerosis at almost every stage of atherogenesis." (PMID 33668632, 2021). "The results provide insights into the pathophysiology of inflammation in stable atherosclerosis, particularly the role of miR-146a in TNF-α-based inflammation in SCAD, and support future research on the potential therapeutic use of miR-146a in such a clinical scenario." (PMID 34199767, 2021). "Therefore, TNF-α has been studied as a therapeutic target in patients with documented atherosclerosis." (PMID 34199767, 2021). "FAK was reported to regulate TNFα and IL1β signaling-induced vascular endothelial adhesion molecule expression and has been demonstrated to be a therapeutic potential in the treatment of vascular inflammatory diseases and atherosclerosis." (PMID 34093519, 2021). "Malnutrition is closely related to inflammation and atherosclerosis, and through common mediators such as IL-6 or TNF-α, it may play a relevant role in ESA hyporesponsiveness." (PMID 33449974, 2021). "Some played essential roles, including AGE-RAGE signaling pathway in diabetic complications, fluid shear stress and atherosclerosis, TNF signaling pathway, hepatitis B, Chagas disease, IL-17 signaling pathway, and Kaposi sarcoma-associated herpesvirus infection." (PMID 34485521, 2021). "Inflammation cells, monocytes and cytokines they release (such as TNF-α, IL-1β, IL-6) have also been found to play an important role in different cardiovascular pathological processes, such as atherosclerosis, myocardial infarction, myocardial remodelling and heart failure, and arrhythmias." (PMID 34957244, 2021). "Importantly, the use of an anti-inflammatory salicylate drug was found to prevent SCI-induced exacerbation of atherosclerosis, possibly via the reduction in TNFα, MCP-1, and CCL-5 plasma levels." (PMID 34571804, 2021). "Hdac9–/–Apoe–/– BMMs have reduced TNF‐α‐induced up‐regulation of pro‐inflammatory gene expression, and during the development of atherosclerosis, HDAC9 binds to, deacetylates and activates inhibitory kappa B kinase (IKK)‐α and β, driving inflammatory responses in macrophages and endothelial cells." (PMID 34145738, 2021). "Besides, inflammatory cytokines including interleukin-1β (IL-1β), IL-6, IL-12, and tumor necrosis factor-alpha (TNF-α) accelerate atherosclerosis progression." (PMID 34239605, 2021).